DNAJB4 (DnaJ heat shock protein family (Hsp40) member B4)
Description:
Probable chaperone. Stimulates ATP hydrolysis and the folding of unfolded proteins mediated by HSPA1A/B (in vitro).
Synonyms: DNAJW; HLJ1; CMYO21; CMYP21; DjB4
Tractability: Antibody: UniProt places it where antibodies can reach, with high confidence; its Gene Ontology location is reachable by antibodies, with high confidence; the Human Protein Atlas places it where antibodies can reach. PROTAC: ubiquitination databases record sites on it; its protein half-life has been measured.
Gene: Protein-coding gene on chromosome 1 (77,979,070 to 78,018,529, forward strand). Ensembl gene ENSG00000162616.
Subcellular location: Cytoplasm; Cell membrane; Cytoplasm, myofibril, sarcomere, Z line
Subcellular location (Human Protein Atlas): Nucleoplasm; Cytosol; Plasma membrane
Gene Ontology:
Molecular function: ATPase activator activity; protein binding; protein-folding chaperone binding
Biological process: negative regulation of transcription by RNA polymerase II; protein folding; response to heat; response to unfolded protein
Cellular component: cytoplasm; cytosol; nucleoplasm; plasma membrane; Z disc
Genetic constraint (gnomAD): Loss-of-function variants: 10 observed, 27.5 expected, observed/expected ratio (o/e) 0.36, 90% interval 0.22 to 0.62. The upper end of that interval is the gene's LOEUF score, 0.62, which puts it in group 2 of 6, group 1 being the genes least tolerant of losing a copy. Missense variants: 328 observed, 431.56 expected, observed/expected ratio (o/e) 0.76, 90% interval 0.69 to 0.83. Synonymous variants: 136 observed, 143.22 expected, observed/expected ratio (o/e) 0.95, 90% interval 0.82 to 1.1.
Homologues: Orthologues: chimpanzee DNAJB4 (100% identical), macaque DNAJB4 (100% identical), rabbit DNAJB4 (97% identical), dog DNAJB4 (97% identical), pig DNAJB4 (97% identical), guinea pig DNAJB4 (96% identical), rat Dnajb4 (96% identical), mouse Dnajb4 (94% identical), tropical clawed frog dnajb4 (81% identical), zebrafish dnajb4 (71% identical), Drosophila melanogaster CG7130 (20% identical). Paralogues in human: DNAJB1 (67% identical), DNAJB5 (65% identical), DNAJB13 (45% identical), DNAJB11 (33% identical), DNAJB6 (31% identical), DNAJB2 (27% identical), DNAJB7 (26% identical), DNAJB12 (24% identical), DNAJB8 (24% identical), DNAJB14 (22% identical), DNAJB9 (20% identical).
Diseases named in the same sentence as DNAJB4 in open-access papers:
DNAJB4 is named in the same sentence as 44 diseases in open-access papers, as found by Europe PMC text mining. Sharing a sentence is not in itself a finding about the gene and the disease. The quoted sentences say what the papers report.
breast carcinoma (13 papers, 2014 to 2025). "The results showed that aberrantly low expression levels of DNAJB4 were likely associated with adverse prognoses in breast cancer." (PMID 37012515, 2023). "Loss or overexpression of DNAJB4 attenuated or enhanced breast cancer cell apoptosis through the Hippo signaling pathway." (PMID 37012515, 2023). "DNAJB4 is expressed at low levels in breast cancer tissues and cell lines, and its low expression is closely related to poor prognosis in patients with breast cancer." (PMID 40149995, 2025). "The Gene Expression Profiling Interactive Analysis (GEPIA) database showed that the DNAJB4 expression was significantly downregulated in breast cancer tissues than normal breast tissues (P < 0.05)." (PMID 37012515, 2023). "To further explore the biological role of DNAJB4 overexpression in breast cancer, we used an overexpression plasmid to stably elevate DNAJB4 expression." (PMID 37012515, 2023). "The reason for the low expression of DNAJB4 in breast cancer is still unclear, but existing evidence suggests that microRNAs have regulatory effects on many genes." (PMID 37548821, 2023). "After DNAJB4 overexpression in MDA-MB-231 breast cancer cells, the efficiency of DNAJB4 overexpression was detected by qRT-PCR and western blot." (PMID 37012515, 2023). "The expression of DNAJB4 was validated in human breast cancer tissues, normal human breast tissues, and breast cancer cell lines." (PMID 37548821, 2023). "In our previous study, we evaluated the expression level of DNAJB4 in breast cancer and its clinical significance through a large number of clinical tissue samples." (PMID 37012515, 2023). "The present study demonstrated that DNAJB4 overexpression inhibited the malignant biological behavior of breast cancer by regulating the Hippo pathway and tumor immunosuppressive environment." (PMID 37548821, 2023). "Recently, it has been reported through bioinformatics research that DNAJB4 is involved in multiple signaling pathways in breast cancer and immune function." (PMID 37012515, 2023). "The DNAJB4 expression in a series of breast cancer cell lines and the normal breast cell was measured by qRT-PCR and western blot analyses." (PMID 37012515, 2023). "The expression levels of DNAJB4 mRNA and protein in 80 breast cancer tissue samples were detected by qRT-PCR, western blot and IHC, respectively." (PMID 37012515, 2023). "DNAJB4 was expressed at low levels in human breast cancer tissues and breast cancer cell lines and correlated with poor prognosis." (PMID 37548821, 2023). "Kaplan‒Meier analysis suggested that low DNAJB4 level was associated with worse distant metastasis-free survival (DMFS) and recurrence-free survival (RFS) in breast cancer patients." (PMID 37548821, 2023). "The database found that when DNAJB4 expression was low, breast cancer patients had a poor prognosis." (PMID 37548821, 2023). "It has been reported that DNAJB4 expression generally tends to decrease in various cancers, such as colorectal cancer, breast cancer, and lung cancer." (PMID 37510314, 2023). "Meanwhile, after overexpression of DNAJB4 in MDA-MB-231 breast cancer cells, the apoptosis of cells was detected by Caspase3/7 activity kit." (PMID 37012515, 2023). "To explore the functional role of DNAJB4 in breast cancer cells, we stably knocked down the expression of DNAJB4 via two DNAJB4-specific lentiviral shRNAs (shDNAJB4 #1 and shDNAJB4 #2) in MDA-MB-231 and BT-549 cells." (PMID 37012515, 2023). "It was found that the apoptosis rate of the MDA-MB-231 breast cancer cells decreased after DNAJB4 knockdown, as well as that of the BT-549 cells." (PMID 37012515, 2023). "DNAJB4 mRNA level is significantly higher in mesenchymal cells than in epithelial breast cancer cells." (PMID 36499297, 2022).
breast carcinoma (continued). "The same researchers showed that the suppression of DnaJB4 in breast cancer cells with a mesenchymal phenotype impaired their migration capacity in vitro and reduced both primary tumor growth and lung metastasis occurrence in vivo." (PMID 32268506, 2020). "Another interesting observation from the present study is that several HSPs were downregulated in all breast cancer subtypes: DNAJB4, DNAJC18, HSPA12A, HSPA12B, HSPB2, HSPB6, and HSPB7." (PMID 29954368, 2018). "Low DNAJB4 expression levels are strongly correlated with poor prognosis in breast cancer patients." (PMID 37548821, 2023). "In addition, we performed immunohistochemical (IHC) staining to evaluate DNAJB4 expression in breast cancer tissue to verify the public dataset results." (PMID 37548821, 2023). "Moreover, normal breast cell line and breast cancer cell lines was used to assess the expression level of DNAJB4." (PMID 37548821, 2023). "Therefore, there is an urgent need to elucidate how DNAJB4 regulates breast cancer progression, providing a basis for in-depth study of breast cancer pathogenesis and the search for new therapeutic targets." (PMID 37548821, 2023). "In addition, the Ki67 and Cleaved Caspase3 expression levels were upregulated in the tumors formed by DNAJB4-downexpressing breast cancer cells compared to DNAJB4 normal-expressing cells." (PMID 37012515, 2023). "Low expression of DNAJB4 is correlated with poor prognosis of breast cancer." (PMID 37548821, 2023). "Bioinformatic analysis was used to identify the DNAJB4 related pathways in breast cancer." (PMID 37548821, 2023). "Moreover, Caspase3/7 activity was also detected in DNAJB4-silenced MDA-MB-231 and BT-549 cells, which confirmed that DNAJB4 knockdown inhibited the breast cancer cell apoptosis." (PMID 37012515, 2023). "The clinical significance of DNAJB4 in breast cancer has been reported in our previous study." (PMID 37012515, 2023). "Thus, to validate the role of the Hippo signaling in the DNAJB4 overexpression-effects against breast cancer progression, we investigated Hippo signaling in MCF-7 cells." (PMID 37548821, 2023). "Through database analysis, we found a significantly downregulated DNAJB4 expression in breast cancer, bladder urothelial carcinoma, colon adenocarcinoma, kidney chromophobe and so on, and DNAJB4 protein level was also decreased in breast cancer tissues and different subclasses." (PMID 37548821, 2023). "However, recent proteomic and patient data analyses have shown that DNAJB4 is a potential metastasis promoter in breast cancer cells." (PMID 36499297, 2022). "It is unknown, however, exactly how DNAJB4 is involved in breast cancer." (PMID 37548821, 2023). "However, the molecular mechanism by which DNAJB4 regulates breast cancer progression is unclear." (PMID 37548821, 2023). "Our findings indicates that DNAJB4 may be a new target for breast cancer therapy." (PMID 37548821, 2023). "Therefore, we suggest that DNAJB4 may play an indispensable role in breast cancer." (PMID 37548821, 2023). "After DNAJB4 was knocked down in the MDA-MB-231 and BT-549 breast cancer cells, the apoptosis of breast cancer cells was detected by flow cytometry." (PMID 37012515, 2023). "After overexpression of DNAJB4 in MDA-MB-231 breast cancer cells, the apoptosis rate of the breast cancer cells was detected by flow cytometry and was found to be increased." (PMID 37012515, 2023). "Our results found that DNAJB4 expression was downregulated in breast cancer tissues and lower in luminal-like cell lines MCF7 than basal-like MDA-MB-231 cell, and DNAJB4 overexpression enhanced the proliferation and migration ability of MCF-7." (PMID 37548821, 2023).
breast carcinoma (continued). "DNAJB4 (HLJ1) is an HSP40 family member that has previously been identified as a tumor suppressor gene in lung, colon, and breast cancer patients, and that has also been specifically identified as a promising therapeutic target and putative biomarker in NSCLC." (PMID 35974419, 2022). "In particular, the knockdown of DNAJB4 in highly metastatic MDA-MB-231 cells can decrease the migration and metastasis of breast cancer cells and suppress the primary tumor growth rate." (PMID 36499297, 2022). "DnaJ homolog subfamily B member 4 (DNAJB4), also called HLJ1, has been proven to serve as a tumor suppressor role in many types of cancer including lung cancer, melanoma, and breast cancer." (PMID 34930465, 2021). "The recent proteomic investigations identified another member of the HSP40 subfamily, DnaJB4, as a new driver of EMT in breast cancer." (PMID 32268506, 2020). "DNAJB4 overexpression activates the Hippo signaling pathway, inhibits cancer cell proliferation and migration, and promotes TNBC cell apoptosis, suggesting its potential as a tumor suppressor and therapeutic target in breast cancer." (PMID 40149995, 2025). "The expression of DNAJB4 in normal breast cells, breast cancer cells, four-paired TNBC tissues, and adjacent noncancerous tissues was quantified by quantitative real-time polymerase chain reaction (qRT-PCR) and western blot assay." (PMID 37012515, 2023). "When DNAJB4 was knocked down and then overexpressed in MDA-MB-231 and BT-549 breast cancer cells, Western blot analysis showed that the phosphorylation levels of MST1, LATS1, and YAP were restored, while the total protein expression of MST1, LATS1, and YAP1 remained unchanged." (PMID 37012515, 2023). "However, the expression levels of DNAJB4 and DNAJB6 in 52 breast cancer cell lines were significantly elevated in aggressive TNBC cell lines compared with DNAJB9." (PMID 33966034, 2021). "Similarly the uPAR specifically bound to MRJ (DNAJB6), but not to DNAJB4 (another MRJ family member) in a breast cancer cell line MDA-MB-231 by using co-IP assay." (PMID 25175595, 2014). "In addition, the expression levels of DNAJB4 and DNAJB6 showed no significant influence on the OS and DMFS of patients with breast cancer." (PMID 33966034, 2021).
lung carcinoma (13 papers, 2009 to 2024). "For instance, DNAJB4 is upregulated in SKCM metastasis, and its loss can inhibit EMT and reduce lung cancer metastasis." (PMID 37548821, 2023). "As a mechanism, the YY1 transcriptional factor can positively regulate DNAJB4 expression, thus reducing lung cancer cell invasive ability by upregulating E-cadherin expression." (PMID 36499297, 2022). "Curcumin can inhibit the migration, invasion, and metastasis of lung cancer cells by activating DNAJB4, similar to andrographolide." (PMID 36499297, 2022). "Curcumin (diferuloylmethane), the most active component of turmeric, can induce DNAJB4 through the activation of JunD as a composition of the AP-1 transcription factor complex and suppress the invasion and metastasis of lung cancer cells." (PMID 36499297, 2022). "In a study with mice lung cancer, curcumin has been demonstrated to up-regulate the expression of E-cadherin through activation of heat shock protein 40 (HLJ1) also known as DNAJB4." (PMID 31817718, 2019). "High DNAJB4 levels can slow down lung cancer cell cycle progression through the STAT1/P21 pathway." (PMID 35478955, 2022). "Moreover, DNAJB4 overexpression can inhibit the proliferation, tumorigenesis, cell mortality, and invasion of lung cancer cells by reducing cyclin D1 expression, increasing STAT1 and p21WAF1 expression, and then activating the STAT1 pathway." (PMID 36499297, 2022). "Further investigations on the mechanism of action of DNAJB4 on tumor progression, particularly on its role in apoptosis of lung cancer cells exposed to UV stress, has indicated that DNAJB4 promotes UV induced apoptosis through JNK and caspase-3 activation in NSCLC cell line." (PMID 21255413, 2011). "DNAJB4 and Src SH3 domains interact to form carcinogenic complexes, which in turn affect the metastasis of lung cancer." (PMID 37548821, 2023). "On the contrary, DNAJB4 (also known as HLJ1) is a tumor suppressor that can inhibit the proliferation and invasion of lung cancer cells." (PMID 35478955, 2022). "One study showed that overexpression of DNAJB4 indirectly upregulated the expression of E-cadherin or regulated the complex formation of NPM1 and inhibited cell invasion and migration in highly invasive lung cancer." (PMID 37510314, 2023).
non-small cell lung carcinoma (8 papers, 2011 to 2025). A group of at least three distinct histological types of lung cancer, including non-small cell squamous cell carcinoma, adenocarcinoma, and large cell carcinoma. "Overexpression of YY1 can induce DNAJB4 transcription by directly binding to the promoter region, which inhibits the invasive ability of non-small-cell lung carcinoma (NSCLC) cells." (PMID 36499297, 2022). "DNAJB4 has been recently identified as a novel tumor suppressor of non-small-cell lung cancer (NSCLC) that can inhibit cancer cell cycle progression, proliferation, invasion and tumorigenesis." (PMID 21255413, 2011). "In addition to breast, bladder, and non-small cell lung cancers, the role of DNAJB4 has also been reported in gastric cancer, although only in animal and cell experiments." (PMID 40149995, 2025).
gastric cancer (6 papers, 2016 to 2025). A primary or metastatic malignant neoplasm involving the stomach. "Subgroup analysis revealed that in patients with advanced gastric cancer, high DNAJB4 expression was associated with increased caspase-3 levels and with elevated CD31 and decreased E-cadherin levels." (PMID 40149995, 2025). "High DNAJB4 expression in gastric cancer is associated with increased CD31 expression, a key marker of angiogenesis, but is inversely associated with advanced cancer stage." (PMID 40149995, 2025). "This study aimed to analyze DNAJB4 expression in gastric cancer and explore its association with clinical characteristics, molecular markers, and patient outcomes." (PMID 40149995, 2025). "In general, our results support that high DNAJB4 expression in gastric cancer is associated with increased levels of CD31, a key marker of angiogenesis, but is negatively correlated with advanced-stage cancer." (PMID 40149995, 2025). "This suggests that high DNAJB4 expression is associated with better long-term outcomes and may play a protective role against gastric cancer progression." (PMID 40149995, 2025). "Subgroup analysis of patients with advanced gastric cancer showed that high DNAJB4 expression was associated with elevated levels of caspase-3, which promotes apoptosis, as well as increased CD31 and decreased E-cad levels, both of which contribute to poor tumor outcomes." (PMID 40149995, 2025). "Additionally, the down-regulated DNAJB4, which is implicated in human gastric carcinomas, and SLIT2, which is involved in pancreatic cancer, are also annotated as tumor suppressors, suggesting their potential roles in UVB-induced skin cancers." (PMID 27829444, 2016). "The current study found distinct differences between patients with gastric cancer with low and with high DNAJB4 expression." (PMID 40149995, 2025). "In an earlier study, CD31 was recognized as an important marker of angiogenesis, but this alone cannot explain the protective effect of high DNAJB4 expression in patients with gastric cancer." (PMID 40149995, 2025). "Concurrent downregulation of DNAJB4 and E-cad is commonly observed in gastric cancer samples, highlighting their cooperative role in suppressing cancer progression and making DNAJB4 a potential therapeutic target." (PMID 40149995, 2025). "Although there have been previous studies on DNAJB4 in gastric cancer models, these were only in animal and cellular models." (PMID 40149995, 2025). "Further studies, including larger multicenter cohorts and mechanistic investigations, are needed to validate the findings and clarify the role of DNAJB4 in gastric cancer." (PMID 40149995, 2025). "DnaJB4 (HLJ1) is another member of the DnaJ family of Hsps and is regarded as a tumor suppressor gene in several cancers, including lung, colon, and gastric cancers." (PMID 35570564, 2022). "However, despite the importance of DNAJB4 expression in cancer, its specific role in gastric cancer has remained largely underexplored." (PMID 40149995, 2025). "Particularly, DNAJB4 plays a crucial tumor-suppressive role in gastric cancer." (PMID 40149995, 2025). "Thus, this study aimed to analyze DNAJB4 expression in gastric cancer and investigate its correlation with prognosis." (PMID 40149995, 2025). "The DNAJB4 gene (also known as HLJ1) belongs to the DNJ family heat shock proteins (HSPs) and is regarded as a tumour-suppressor in COAD, BRCA, lung, and gastric cancer." (PMID 34681112, 2021). "DNAJB4 has been shown to have prognostic implications in other cancer types; however, its expression patterns and role in gastric cancer have not been extensively studied." (PMID 40149995, 2025). "Finally, DNAJB4 is a DNAJ family protein for which tumor suppressor activity has been demonstrated in breast, lung and gastric cancers." (PMID 35406724, 2022).